MTDH (metadherin)
Diseases named in the same sentence as MTDH in open-access papers (continued):
Sharing a sentence is not in itself a finding about the gene and the disease.
prostate carcinoma (48 papers, 2009 to 2025). A carcinoma that arises from epithelial cells of the prostate gland. "The present study aimed to elucidate the effects of MTDH as an oncogene associated with the biological behavior of prostate cancer cells and chemotherapy-sensitivity to cisplatin in vitro." (PMID 25684730, 2015). "Increased MTDH expression is also implicated in prostate cancer." (PMID 31131259, 2019). "However, at present, few investigations into MTDH-associated prostate cancer have been performed." (PMID 25684730, 2015). "highlighted that miR‐145‐3p or miR‐145‐5p‐mediated suppression of MTDH expression inhibited prostate cancer cell growth and metastasis." (PMID 40223182, 2025). "They identified miR-145-5p and miR-145-3p from a set of 16 miRNAs that are closely related to prostate cancer and are targets of MTDH; both miRNAs significantly inhibit prostate cancer cell growth and metastasis by negatively regulating MTDH expression." (PMID 40689207, 2025). "miR-145-3p or miR-145-5p hinders the proliferation and metastasis of prostate cancer cells through MTDH suppression." (PMID 35936390, 2022). "Although MTDH is obviously expressed in the cytoplasm in breast tumors, the existence of a nuclear MTDH expression in prostate cancer and NIH3T3 cells has been reported previously." (PMID 33003428, 2020). "YTHDC1 has been shown to interact strongly with the metadherin (MTDH) oncoprotein in prostate cancer, suggesting its role in cancer proliferation and tumorigenesis." (PMID 32709063, 2020). "During prostate cancer development, metadherin has been shown to translocate from the nucleus to the cytoplasm, indicating that an important nuclear role of metadherin is lost during prostate tumourigenesis." (PMID 31450747, 2019). "It was demonstrated that the inhibition of MTDH expression promoted cell apoptosis, reduced cell viability and weakened the invasive ability of prostate cancer cells." (PMID 25684730, 2015). "A previous study suggested that MTDH was expressed at higher levels in prostate cancer samples, compared with those of benign prostatic hyperplasia." (PMID 25684730, 2015). "MTDH knockdown induces apoptosis of prostate cancer cells through the attenuation of Akt activity and upregulation of FOXO3a activity." (PMID 22768080, 2012). "CircHIPK3 regulates prostate cancer progression through targeting miR-448/MTDH axis." (PMID 35443871, 2022). "miR-145-3p restrains the growth of prostate cancer cells by targeting MTDH." (PMID 35936390, 2022). "MTDH acts as an oncogene in prostate cancer and is related to the poor prognosis of patients." (PMID 34504842, 2021). "Similarly, miR-342-3p functions as a tumor suppressor by targeting MTDH in human osteosarcoma and prostate cancer." (PMID 31131259, 2019). "Finally, we attempted to confirm our observations in a clinical context, finding increased CD44v5 expression in prostate cancer patients who have high metadherin expression." (PMID 31450747, 2019). "Finally, we demonstrate that prostate cancer patients with higher metadherin expression have greater expression of the CD44v5 exon." (PMID 31450747, 2019). "In this same prostate cancer cohort, there were also frequent CNGs of MTDH and ESRP1." (PMID 27029057, 2016). "Genomic amplification of MTDH has been detected in breast and prostate cancers." (PMID 25333261, 2014). "Expression analysis revealed that MTDH expression is significantly higher in melanoma, breast, esophageal, gastric, hepatocellular, endometrial and prostate cancers, renal cell carcinoma, neuroblasoma and malignant glioma cell lines compared with their normal counterparts." (PMID 22768080, 2012). "As we saw altered expression of T-STAR in prostate cancer, we used a panel of prostate cell lines to examine the protein expression of alternative splicing components, specifically Sam68, T-STAR, YTHDC1 and metadherin." (PMID 31450747, 2019).
prostate carcinoma (continued). "Using a yeast two-hybrid assay and immunoprecipitation we show that metadherin interacts with YTHDC1, Sam68 and T-STAR and demonstrate that T-STAR is significantly overexpressed in prostate cancer tissue compared to benign prostate tissue." (PMID 31450747, 2019). "MTDH also activates the PI3K/Akt pro-apoptotic pathway in cancer and its inhibition induces apoptosis in prostate cancer cells." (PMID 27755556, 2016). "Our previous studies revealed that tumor-suppressive miR-145-3p was closely involved in human cancer pathogenesis by targeting oncogenes, for example, MTDH in LUSQ; MELK, NCAPG, BUB1, and CDK1 in prostate cancer; MYO1B in head and neck cancer; and MYO1B and DHRS2 in esophageal cancer." (PMID 31514295, 2019). "Furthermore, Kyoto Encyclopedia of Genes and Genomes (KEGG) pathway analysis revealed that genes influenced by MTDH overexpression were mostly enriched in pathways involved in PI3K-AKT signaling, prostate cancer, extracellular matrix (ECM)-receptor interactions and focal adhesion." (PMID 31978894, 2020).
gastric cancer (35 papers, 2012 to 2025). A primary or metastatic malignant neoplasm involving the stomach. "While the IAA-AHR axis demonstrates pro-inflammatory effects (activating p38MAPK/NF-κB) in kidney diseases 38, this study reveals that it exerts anti-inflammatory effects in gastric cancer (inhibiting NF-κB via MTDH)." (PMID 41208900, 2025). "AHR activation inhibits MTDH phosphorylation at Ser298, which in turn suppresses nuclear factor kappa B (NF-κB) signaling pathway activity, ultimately attenuating gastric cancer progression." (PMID 41208900, 2025). "Increased levels of this miRNA suppress the proliferation and metastasis of gastric cancer cells by targeting metadherin (MTDH) and inhibiting the NF-κB signaling pathway." (PMID 39931465, 2025). "In summary, our study revealed the vital role of the circALPL-miR-127- MTDH axis in gastric cancer progression." (PMID 34234862, 2021). "The results showed that circALPL promotes gastric cancer progression by sponging miR-127, thus upregulating MTDH." (PMID 34234862, 2021). "Differentially, expression of miR-384 was diagnosed in multiple cancers, for instance, overexpression of miR-384 inhibited gastric cancer cell growth, migration, and invasion by interacting with metadherin." (PMID 33817254, 2020). "Recently, hsa-miR-3664-5p was found to suppress the proliferation of gastric cancer through its target MTDH." (PMID 32616021, 2020). "Currently, numerous studies have evaluated the prognostic significance of markers, such as the p16, Bcl-2, MTDH and c-myc genes in gastric cancer." (PMID 23599799, 2013). "MTDH promotes inflammation in the tumor microenvironment in gastric cancer." (PMID 34234862, 2021). "Accordingly, the downregulation of MTDH expression could induce remodeling of the actin cytoskeleton and inhibit epithelial-mesenchymal transition in gastric cancer cell lines (MKN45 and AGS)." (PMID 31131259, 2019). "In gastric cancer, studies showed that knockdown of MTDH by siRNA in SGC790 cells could apparently inhibit cell proliferation by blocking cell cycle in G0/G1 phase." (PMID 30227879, 2018). "AEG-1/MTDH overexpression is associated with TNM Stage (TNM Classification of Malignant Tumors), Ki-67 proliferation index and poor survival, and is an independent prognostic factor for gastric cancer in multivariate analysis." (PMID 25009642, 2014). "AEG-1/MTDH overexpression is a useful prognostic factor in patients with gastric cancer, and the inhibition of AEG-1/MTDH may provide a novel therapeutic strategy for gastric cancer." (PMID 25009642, 2014). "At the transcriptional level, AEG-1/MTDH levels may be increased in gastric cancer tissue samples, but with considerable heterogeneity, and it may have the potential to be used as a target for diagnostic/therapeutic purposes only in a subset of patients." (PMID 25009642, 2014). "The high expression of AEG-1/MTDH is observed in gastric cancer tissues." (PMID 25009642, 2014). "In gastric cancer inhibition of MTDH may decrease the level of β-catenin and inactivate Wnt/β-catenin pathway through reducing phosphorylation of AKT and glycogen synthase kinase (GSK)-3β (Ser 9)." (PMID 22768080, 2012). "Inhibition of MTDH expression by specific siRNA clearly decreased the level of β-catenin and it may play a role in Wnt/β-catenin-mediated gastric cancer progression." (PMID 22768080, 2012). "Interestingly, MTDH silencing in gastric cancer cells regulates actin cytoskeletal remodeling." (PMID 34277708, 2021). "MTDH, also known as AEG-1 (Astrocyte Elevated Gene 1) and Lyric, has been implicated in the development and progression of a variety of human cancers, including hepatic cancer, lung cancer, esophageal squamous cell carcinoma, glioblastoma multiforme, and gastric cancer." (PMID 32074085, 2020). "Similarly, upregulation of MTDH in gastric cancer may occur as a consequence of reduced miR-22 expression." (PMID 31131259, 2019).
gastric cancer (continued). "Therefore, the status of AEG-1/MTDH expression and its significance in gastric cancer remains unclear and requires further investigation." (PMID 25009642, 2014).
colorectal cancer (31 papers, 2012 to 2026). A primary or metastatic malignant neoplasm that affects the colon or rectum. "Previous reports also described that high MTDH expression is closely linked to poor prognosis in breast, hepatocellular, esophageal and colorectal cancers." (PMID 29029495, 2017). "RARRES3 can also participate in the regulation of hepatocarcinogenesis through the miR-1/G9a/RARRES3 axis, and in the regulation of epithelial-mesenchymal transition in colorectal cancer through the inhibition of MTDH." (PMID 38375157, 2024). "Metadherin/AEG1 whole-body knockdown studies in prostate, liver, lung, and colorectal cancers yielded similar results." (PMID 38253625, 2024). "The lncRNA HCG18 promoted the growth and invasion of colorectal cancer cells through sponging miR-1271 and upregulating MTDH." (PMID 36595551, 2023). "Ghafar suggested that the Wnt cascade is activated by MTDH, and exerts oncogenic functions in colorectal cancer." (PMID 35115027, 2022). "It is also overexpressed in colorectal cancer tissues and cell lines and can enhance MTDH/Wnt/β-catenin signaling through the sponging of miR-1271, thereby exerting potential carcinogenic effects." (PMID 34615480, 2021). "The oncoprotein AEG-1, encoded by the MTDH gene, was shown previously to be involved in colorectal cancer (CRC)." (PMID 26983693, 2016). "HCG18 could sponge with miR-1271, subsequentially activate MTDH/Wnt/β-catenin pathway, and ultimately fascinate the growth and invasion of colorectal cancer." (PMID 35389764, 2022). "Interestingly, m6A RNA methylation was reported to regulate T cell-mediated pathogenesis and immunotherapy sensitivity in colorectal cancer and melanoma and implied that the positive correlation of m6A RNA methylation with MTDH might contribute to the mechanism of MTDH in immunotherapy resistance." (PMID 34622157, 2021). "The potential role of AEG-1/MTDH is to promote tumor progression and metastasis in human HCC cell lines and colorectal cancer (CRC)." (PMID 25009642, 2014). "AEG-1/MTDH-knockdown decreases nuclear β-catenin accumulation and suppresses the migration and invasion of SW620 colorectal carcinoma cell lines." (PMID 25009642, 2014). "For instance, Metadherin (AEG-1/MTDH/LYRIC) has been closely related to the poor prognosis of colorectal cancer, and can be used as a marker for the clinical diagnosis and a potential target for the treatment of colorectal cancer." (PMID 35918714, 2022).
ovarian carcinoma (27 papers, 2012 to 2025). A malignant neoplasm originating from the surface ovarian epithelium. "Recently study showed MTDH exon 11 skipping variant can be considered a major promalignant factor for ovarian cancer." (PMID 25993398, 2015). "Strong p50, p65, and metadherin expression was associated with a high probability to distinguish ovarian carcinomas over borderline and benign ovarian tumours, as well as borderline ovarian tumours over benign ovarian neoplasms." (PMID 24963474, 2014). "We expect that MTDH will be a useful molecular marker for assessing ovarian cancer risk and for predicting ovarian cancer patient prognosis." (PMID 23240043, 2012). "We found that the MTDH (−470G>A) polymorphism was statistically correlated with ovarian cancer risk (under the additive genetic model, GG vs. GA vs AA, P = 0.042)." (PMID 23240043, 2012). "High MTDH expression was associated with the progression and prognosis of ovarian cancer." (PMID 23240043, 2012). "The MTDH (−470G>A) genotype & Allele distribution in Ovarian Cancer and controls." (PMID 23240043, 2012). "Therefore, the association of the MTDH (−470G>A) polymorphism with MTDH promoter activeity and its effect on ovarian cancer development should be studied in vitro to further investigate the molecular mechanisms involved." (PMID 23240043, 2012). "Thus, we investigated the association of MTDH (−470G>A) polymorphism with ovarian cancer development in 145 ovarian cancer patients and 254 matched control subjects, using sequence analysis." (PMID 23240043, 2012). "In conclusion, the A allele of the MTDH SNP rs16896059 (−470G>A) is protective against ovarian cancer, and the homozygous AA genotype may be a protective genotype." (PMID 23240043, 2012). "However, the relationship between MTDH polymorphism and ovarian cancer risk requires further investigation in different ethnic populations." (PMID 23240043, 2012). "In conclusion, our study highlights the heterogeneity of ovarian cancer and identifies MTDH as a protein of interest in its progression." (PMID 41286067, 2025). "Here using a biotinylation assay and subsequent Western blotting, we demonstrated the upregulation of the relatively uncommon cell surface metadherin in the highly metastatic ovarian cancer cells." (PMID 35403834, 2022). "In recent years, metadherin (MTDH), an oncogene implicated in cancerogenesis, has been recognized as a remarkable prognostic marker of several malignancies such as ovarian cancer." (PMID 36675955, 2022). "Meanwhile, a total of 55 potentially relevant papers were excluded as they were against the inclusion criteria of our meta-analysis, of which three studies only investigated the gene expression of MTDH in breast and ovarian cancer." (PMID 27917902, 2016). "AEG-1/MTDH overexpression has also been documented in melanoma, neuroblastoma, osteosarcoma and ovarian cancer, as well as in other tumors." (PMID 25009642, 2014). "In a large proportion of epithelial ovarian cancer patients with peritoneal dissemination and/or lymph node metastasis, AEG-1/MTDH is overexpressed and is a novel predictor of metastasis." (PMID 25009642, 2014). "Our results support the potential diagnostic significance of AEG-1/MTDH, p50, and p65 expression in the differential diagnosis of ovarian carcinomas over borderline and benign epithelial ovarian tumours." (PMID 24963474, 2014). "We found that MTDH level was significantly higher in ovarian cancer cells than in normal epithelial cells." (PMID 25333261, 2014).
ovarian carcinoma (continued). "In this study we investigated the expression pattern of the subunits of NF-κB, p50 and p65, and AEG-1/MTDH, a transcription coactivator of NF-κB in ovarian carcinomas, borderline ovarian tumours, and benign cystadenomas." (PMID 24963474, 2014). "Ovarian carcinomas expressed statistically significant higher levels of AEG-1/MTDH protein compared to benign tumours, and borderline ovarian tumours (Mann Whitney U-test, P < 0.001)." (PMID 24963474, 2014). "We assessed the immunohistochemical expression of p50, p65, and metadherin in 30 ovarian carcinomas, 15 borderline ovarian tumours, and 31 benign ovarian cystadenomas." (PMID 24963474, 2014). "In this study, we further analyzed various SNPs in MTDH and found another SNP (rs16896059, −470G>A) with statistically significant differences between ovarian cancer case and control groups." (PMID 23240043, 2012). "As previously reported, the expression levels of MTDH in ovarian cancer tissues were significantly higher than the levels in adjacent normal tissues (P<0.0001)." (PMID 23240043, 2012). "The levels of MTDH protein in 15 ovarian cancer tissues were significantly higher than those in 17 normal tissues (P<0.01)." (PMID 23240043, 2012). "Thus, the MTDH (−470G>A) polymorphism may be an indicator of clinical stage in ovarian cancer." (PMID 23240043, 2012). "To date, only one study has revealed a negative association between MTDH (− 470G > A) polymorphism and ovarian cancer susceptibility." (PMID 38977630, 2024). "High AEG-1/MTDH expression was associated with a 98.4% probability of accurately distinguishing ovarian carcinomas from nonmalignant tumours." (PMID 24963474, 2014). "To explore whether MTDH is involved in miR-145 induced suppression of ovarian cancer cell proliferation and invasion, we performed rescue experiment of MTDH overexpression in miR-145 ectopically expressed cells and corresponding control cells." (PMID 25333261, 2014). "AEG-1/MTDH expression may also aid the differential diagnosis between borderline and ovarian carcinomas." (PMID 24963474, 2014). "Furthermore, overexpression of MTDH rescued the inhibitory effects of miR-145 in ovarian cancer cells." (PMID 25333261, 2014). "Finally, we used the binary logistic regression model to investigate the predictive value of p50, p65, and AEG-1/MTDH expression levels in the diagnosis of ovarian carcinomas." (PMID 24963474, 2014). "We then attempted to test whether restoration of MTDH could reverse the miR-145 mediated inhibition of metastatic ability of ovarian cancer cells." (PMID 25333261, 2014). "To investigate whether MTDH contributes to HGSOC, we first examined the MTDH expression in ovarian cancer cell lines and primary HGSOC tissues." (PMID 25333261, 2014). "However, one study did reveal a negative association between the MTDH (− 470G > A) polymorphism and ovarian cancer susceptibility." (PMID 38977630, 2024). "However, no studies assessing MTDH gene polymorphisms and their potential relationship to ovarian cancer susceptibility have been reported." (PMID 23240043, 2012). "However, the association of MTDH variants with ovarian cancer susceptibility has not been investigated." (PMID 23240043, 2012). "Notably, the MTDH protein itself was also found at high levels in KURAMOCHI, showing a similar pattern to the S568 phosphosite across the panel of ovarian cancer cell lines, though with slightly less variation between the highest and lowest levels." (PMID 41286067, 2025). "In the present study, although we did not perform co-immunoprecipitation in ovarian cancer cells, we provide complementary evidence through immunofluorescence staining and confocal microscopy, demonstrating colocalization of MTDH and SND1." (PMID 41286067, 2025).